IL6 (interleukin 6)
Diseases named in the same sentence as IL6 in open-access papers (continued):
Sharing a sentence is not in itself a finding about the gene and the disease.
cancer (continued). "Here the authors propose the protein and mRNA of RasGRP1 have opposing functions by promoting IL-6 mediated acute inflammation and inhibiting inflammation-associated cancer through mRNA and protein mechanisms respectively." (PMID 36385095, 2022). "IL‐1β is secreted by infiltrating neutrophils and induces IL‐6 production by intestinal mononuclear phagocytes, promoting tumorigenesis in colitis‐associated cancer mouse models." (PMID 35791509, 2022). "In agreement with the previous studies, SZU251 + MUC1 caused a rapid induction of common cytokines such as IL6, TNFα and IFNγ in mouse BMDCs and spleen lymphocytes in vitro, favoring Th1-mediated immune responses and cytotoxic T cells acting on cancer cells." (PMID 36499455, 2022). "This observational study aimed to investigate the association between IL-6, IL-8, and TNFα genetic single nucleotide polymorphisms (SNPs) and response to opioid therapy in a cohort of pediatric cancer patients." (PMID 35335997, 2022). "In a mouse model of cancer-induced cachexia, muscle wasting was associated with higher levels of circulating IL-6." (PMID 36588738, 2022). "As described in noncancer patients, elevated neutrophil counts, depleted lymphocyte counts, elevated D‐dimer levels, and serum inflammatory markers (e.g., IL‐6) were associated with poor clinical outcomes in our cancer population." (PMID 35470980, 2022). "On the other hand, cancer and chemotherapy-associated persistent fatigue is correlated with the increased levels of IL-1 and IL-6." (PMID 35273508, 2022). "Studies have shown that alterations in genes encoding pro-inflammatory cytokines (IL-1β, IL-6) and their high concentrations greatly contribute to the occurrence, intensity, and severity of various symptoms in cancer patients." (PMID 36067147, 2022). "The enhanced migration of cancer cells caused by coculturing with fibroblasts was canceled by the IL-6 neutralizing antibody." (PMID 35089951, 2022). "Cancer-associated fibroblasts stimulate Tregs chemoattraction and enhance Tregs accumulation and growth by releasing IL6." (PMID 34968167, 2022). "Interleukin-6 (IL-6) was proved to induce adipose tissue loss in patients with cancer cachexia by promoting lipolysis and WAT browning." (PMID 36316707, 2022). "Activation of the JAK/STAT pathway, which is downstream from IL-6, has been associated with cancer cachexia." (PMID 36358681, 2022). "CRP, dNLR, YKL-40, and IL-6 are biomarkers of systemic inflammation and elevated plasma levels are frequently seen in several age-related conditions, like cancer, and associated with the presence of vulnerability and frailty in older adults." (PMID 36233472, 2022). "We observed that accumulative evidence has demonstrated that the IL-6/JAK/STAT3 pathway is aberrantly hyperactivated in many types of cancer and such hyperactivation is generally associated with a poor clinical prognosis." (PMID 35756644, 2022). "The central mechanism behind cancer-associated cachexia is inflammation involving the overproduction of inflammatory cytokines, especially IL-6, TNF-α, and IL-1β." (PMID 36505042, 2022). "TAMs can release arachidonic acid, tumor necrosis factor-α (TNF-α), TGF-β, and IL-6 in melanoma, causing cancer cells to produce VEGF-A, which accelerates angiogenesis." (PMID 36072596, 2022). "The leading cause of FID in cancer is the release of pro-inflammatory cytokines associated with cancer, such as IL-6, IL-1, tumor necrosis factor α (TNF-α), and interferon-γ (IFN-γ)." (PMID 36567722, 2022). "Laboratory experiments have reported that IL-6 induces skeletal muscle atrophy, and the inhibition of IL-6 can attenuate skeletal muscle atrophy caused by denervation, cancer cachexia, and disuse." (PMID 35528525, 2022). "Il6 high production, indeed, causes a rich inflammatory environment and can promote the malignant transformation of cancer cells supporting their proliferation, survival, and metastatic dissemination." (PMID 36564370, 2022).
cancer (continued). "Previous studies have also demonstrated that ICB therapy increase IL-6 levels in cancer patients, what has been associated with worse prognosis." (PMID 36443756, 2022). "In the Whitehall II study cohort, Ridker demonstrated that low level of systemic inflammation detected by increased levels of CRP and IL-6 was associated with prediction of cardiovascular and cancer-related mortality in midlife patients." (PMID 35911555, 2022). "IL-6 causes uncontrolled inflammatory responses resulting in chronic inflammation and even carcinoma." (PMID 35924148, 2022). "Recent experimental studies on cancer tissue and on the healing tissue beneath burns showed that inflammation, provoked by high level of IL-6, increase expression of UCP1 and predispose to catabolic changes in AT." (PMID 34067093, 2021). "Elevated CRP/IL6 levels in the serum are a hallmark of inflammatory and aggressive cancers, particularly associated with lung, colon, and ovarian cancers." (PMID 33708198, 2021). "IL6 is a key player in multiple pathophysiological properties associated with cancer progression and drug resistance." (PMID 34094941, 2021). "Macrophages and cancer-associated fibroblasts, as parts of the spheroid, are able to release IL-6 and TGFβ, which contribute to the resistance of lung cancer cells to ionizing radiation and cytotoxic drugs." (PMID 34950592, 2021). "Cancer-associated adipocytes secrete inflammatory cytokines such as interleukin (IL)-6 and tumor necrosis factor (TNF)-α, which are known to promote cancer progression by contributing to pro-cancer inflammation." (PMID 34071012, 2021). "IL-6 is implicated in chronic inflammation and cancer and is one potential therapeutic target for intervention (López-Mejías and González-Gay 2019)." (PMID 34236518, 2021). "Previous research identified the role of IL-6 as a driver of tumorigenesis and anti-apoptosis signaling and a vital biomarker of cancer diagnosis, risk, and prognosis." (PMID 35155571, 2021). "In the TME, cancer-associated fibroblasts (CAFs) can promote and maintain the stem cell-like properties of liver cancer cells through the IL-6/STAT3/Notch signaling pathway." (PMID 34447750, 2021). "Interleukin-6 (IL-6) is a pro-inflammatory cytokine associated with skeletal muscle wasting in cancer cachexia." (PMID 34944037, 2021). "Elevated IL-6 level is linked to chronic inflammatory conditions and observed in many types of cancers." (PMID 34093869, 2021). "A number of meta-analysis of the IL-6 gene polymorphisms with cancer risk were conducted based on small sample sizes." (PMID 33684135, 2021). "The decreased level of albumin correlated with the production of pro-inflammatory cytokines, such as interleukin-6, a cytokine associated with progression of cancers." (PMID 33608012, 2021). "Genetic variants at the promoter region of the IL-6 gene can result in variations in transcription and influence the susceptibility to various cancers." (PMID 34582655, 2021). "IFN-γ and interleukin 6 (IL-6) are among the most important cytokines associated with immune response in cancer." (PMID 34867958, 2021). "A positive association exists between endogenous COX-2 metabolites and IL-6 synthesis in both in vitro and in vivo models of several types of malignant neoplasms." (PMID 34178680, 2021). "Seventeen studies reported the association between polymorphism rs1800797 and cancer risk, and twelve studies reported the association between IL-6 promoter polymorphisms and cancer prognosis." (PMID 34684062, 2021). "One of the mediators that trigger the STAT3 signaling pathway is IL-6, which plays a role in inflammation-associated cancer." (PMID 34572138, 2021). "This is somewhat surprising since post-exercise increases in serum concentrations of myokines (skeletal muscle-derived cytokines/peptides), such as interleukin (IL)-6, have previously been associated with cancer cell apoptosis in vitro." (PMID 33864493, 2021).
cancer (continued). "This transition is implicated in the regulation of metastasis and cancer progression and is driven by the IL-6/JAK2/STAT3 pathway in lung and ovarian carcinomas." (PMID 34207510, 2021). "IL-6 is expressed in ERG-positive cancers in which its up-regulation is caused by prostaglandin receptor E2." (PMID 34204596, 2021). "TNF-α and IL-6 are both pleiotropic cytokines playing major roles in cancer-associated cytokine networks." (PMID 33461943, 2021). "While IL-6 likely executes its immune-suppressive properties through the regulation of multiple immune processes, our data demonstrate that loss of IL-6 enhances the generation of anti-cancer immunity in response to multiple immune-stimulating therapies." (PMID 34711820, 2021). "Interleukin-6 (IL-6) gene encodes a cytokine that functions in inflammation and has been reported in association with cancers in the literature for many years." (PMID 33684135, 2021). "The IL6/JAK/STAT3 pathway is hyperactivated in various types of cancer and is commonly associated with poor clinical prognosis." (PMID 35008199, 2021). "Recently, a meta-analysis was performed on 97 original research covering IL-6 promoter SNPs and noticed a significant association with cancer risk and prognosis." (PMID 34327025, 2021). "Results from this Meta-analysis indicated a significant association (p-value < 0.05) of the IL-6 gene rs1800796 polymorphism with an overall increased cancer risk." (PMID 33684135, 2021). "For example, C-reactive protein (CRP), a diagnostic marker of cancer cachexia, is synthesized in the liver in response to systemic IL-6." (PMID 33801569, 2021). "Concordantly, we showed that treatment with recombinant proteins (500 pg/mL MCP-1 in H1299 and 1000 pg/mL IL-6 in H358) significantly restored the anti-cancer effects caused by Hiltonol." (PMID 33562773, 2021). "The IL-6/JAK/STAT3 pathway is aberrantly hyperactivated in many types of cancer, and such hyperactivation is generally associated with a poor clinical prognosis." (PMID 33540700, 2021). "An increasing number of studies are showing that TNF-α and IL-6 are the primary inflammatory cytokines implicated in cancer cachexia, and these have emerged as critical factors related to the loss of muscle mass." (PMID 34724970, 2021). "The IL6-JAK-STAT3 pathway is aberrantly hyperactivated in many cancer types, and such hyperactivation is generally associated with a poor clinical prognosis implying that it can be used as a promising prognosis indicator." (PMID 34660570, 2021). "Interleukin-6 (IL-6) has numerous pro-inflammatory roles and regulates multiple pathways in cancer associated with poor prognosis." (PMID 34944729, 2021). "We found the insignificant heterogeneity of different studies in the analysis of IL-6 -597G/A polymorphism for overall cancer risk under the all genetic models." (PMID 33684135, 2021). "It has been shown in previous studies that the IL-6/JAK STAT3 pathway is abnormally highly activated in many cancers, which is generally associated with poor clinical prognosis." (PMID 33912584, 2021). "The authors concluded that IL-6 and leptin can play the role of early markers of metabolic changes associated with cancer development." (PMID 34572929, 2021). "TNF, BRCA2, MYC, and IL6 are some examples of proteins that are frequently associated with PCa and are also known to function as biomarkers for other types of cancer." (PMID 34771740, 2021). "Results from this study, more confidently showed that the IL-6 gene SNPs (rs1800795, rs1800796 and rs1800797) in humans are associated with increased cancer risks." (PMID 33684135, 2021). "An earlier study that evaluated the association between proinflammatory cytokines and cancer incidence revealed that IL-1β, IL-6, and TNF-α are associated with an increased risk of cancer." (PMID 33869169, 2021). "The Caucasian and mixed ethnic group showed insignificant association of the IL-6 -572G/C polymorphism with the overall cancer risk." (PMID 33684135, 2021).
cancer (continued). "Diverse signalling pathways are involved in carcinogenesis and one of such pathways implicated in many cancers is the interleukin 6/signal transducer and activator of transcription 3 (IL-6/STAT3) signalling pathway." (PMID 34078370, 2021). "Increased serum levels of G-CSF and IL-6 have been associated with a poor prognosis in different type of cancer." (PMID 34572138, 2021). "The IL-6/JAK/STAT3 pathway is also abnormally activated in many types of cancer, which is generally associated with a poor clinical prognosis." (PMID 35155571, 2021). "Inflammatory mediators, such as IL-6, play a crucial role in muscle wasting and in cancer patients high circulating IL-6 levels correlate with weight loss and survival." (PMID 34203023, 2021). "This study first identified the IL6-JAK-STAT3 pathway among various cancer hallmarks as a promising risk hallmark in ccRCC." (PMID 34660570, 2021). "IL-6 and IL-8 are implicated to affect cellular survival in various cancer entities including AML26–31 and associate with disease outcome." (PMID 34504191, 2021). "Increased IL-6 stimulation is common in various cell lines and tumors and is linked to cancer metastasis and cancer cell survival as a result of STAT3 phosphorylation." (PMID 34944867, 2021). "The abnormal hyperactivation of IL6 pathway is usually associated with a poor clinical prognosis in many types of cancer." (PMID 34576335, 2021). "Our studies focused specifically on the dUTPase, since we previously showed that the HERV-K dUTPase can induce IL-6, and IL-6 has been implicated in EndMT in experimental pulmonary hypertension and in epithelial-mesenchymal transition in cancer cells." (PMID 34185707, 2021). "Serum concentrations of IL-6 have repeatedly been linked to age-related morbidities, including cancer and frailty." (PMID 33595649, 2021). "IL-6 is mainly overexpressed in cancer-associated adipocytes (CAA), contributing to the invasive behavior of cancer cells." (PMID 33026575, 2021). "The inflammatory cytokine IL-6 is known to play a causal role in the promotion of cancer, although the underlying mechanisms remain to be completely understood." (PMID 33651821, 2021). "This 9-ARG signature was also significantly associated with the enrichment of cancer hallmarks, including angiogenesis, IL6-KJAK-STAT3 signalling, reactive oxygen species pathway and oxidative phosphorylation." (PMID 34374416, 2021). "Pertaining to cancer hallmark, IL6-JAK-STAT3 signaling pathway and inflammatory response were the most relevant cancer hallmarks." (PMID 35360412, 2021). "The IL‐6/gp130 signaling pathway in preclinical models and human cancer patients has linked autophagy regulation to cancer‐induced inflammation." (PMID 34270178, 2021). "Most interestingly, we found that exosomal COL6A1 derived from OS cells convert normal fibroblasts to cancer-associated fibroblasts (CAFs) by secreting pro-inflammatory cytokines, including IL-6 and IL-8." (PMID 33391546, 2021). "Recently, we have shown that IL-6 secreted by primary cancer-associated fibroblasts (CAFs) isolated from human CCA is capable of inhibiting autophagy in CCA cells and by doing so it stimulates their proliferation and invasive potential." (PMID 33925189, 2021). "Stromal IL-6 and cancer-cell-associated autophagy proteins were assayed by Tissue MicroArray immunohistochemistry and their expression correlated with overall survival (OS) in a cohort of 70 CCA patients." (PMID 33925189, 2021). "One of the best characterized pro-tumorigenic cytokines is interleukin 6 (IL-6), known to be linked to increased risk of development of a large variety of cancers." (PMID 34360868, 2021). "Trans-signalling has been linked to pro-inflammatory effects and the observed role of IL6 in chronic diseases and cancer." (PMID 34834425, 2021).
cancer (continued). "In human cholangiocarcinoma cell lines (KKU-213 and KKU-100), conditioned medium from cancer-associated fibroblasts (CAFs) stimulated the secretion of IL-6, which further helped in the migration of cancer cells." (PMID 34681206, 2021). "The results generated through this meta-analysis showed that the IL-6 -572G/C polymorphism was significantly associated with the overall cancer risk in the case of over-dominant model [CG vs. CC + GG: OR = 1.12, 95% CI = 1.01–1.23, p-value = 0.0288]." (PMID 33684135, 2021). "Increased IL‐6/JAK/STAT3 signalling is implicated in many human cancers and is associated with poor clinical prognosis." (PMID 33382511, 2021). "The IL6-JAK-STAT3 signaling pathway is upregulated in various types of cancer and its hyperactivation is associated with adverse clinical outcome." (PMID 33435173, 2021). "Comparative discussion showed that our multi-case meta-analyses received more support than any previously reported individual meta-analysis about the association between the IL-6 gene polymorphisms and cancer risks." (PMID 33684135, 2021). "In the presence of TGF-β, the expression of core cancer stemness-associated genes was significantly reduced in U251 cells transfected with si-IL6." (PMID 33576874, 2021). "The main cause of FID in cancer is the release of cancer-associated pro-inflammatory cytokines such as interleukin (IL)-6, IL-1, TNF-α, and IFN-γ." (PMID 33777027, 2021). "Knockout of miR-146a leads to excessive production of inflammatory cytokines such as TNF-α and IL-6, which, in turn, induces chronic inflammation and increases susceptibility to cancer and loss of Treg cell function." (PMID 34790566, 2021). "For example, cancer cells produce an overabundance of IL6 or IL10, which is associated with poor prognosis." (PMID 34512714, 2021). "The presence of IL-6 in the TME enhances the glycolysis activities in cancer associated fibroblasts (CAF), enabling them to generate metabolic intermediates to support cancer cells." (PMID 33514004, 2021). "For example, NF-κB activation in cancer cells by inflammatory stimuli results in the production of IL-6, which in turn activates expression of stemness-associated genes through a IL-6−JAK−STAT3 pathway." (PMID 31936290, 2020). "The association of reduced CYP3A4 expression in the presence of cancer is associated with the inflammatory response and the release of cytokines such as IL-6 from the cancer into the blood." (PMID 33076284, 2020). "Acting on the immune system, the mechanisms involved in depression (e.g., a high release of pro-inflammatory molecules) have been suggested to influence cancer progression (e.g., the interleukin-6 plasma level is associated with several types of cancer)." (PMID 32962202, 2020). "It seems that more activation of IL6 which is associated with its upregulation in the case of GERD can be considered as a cancer risk factor." (PMID 33585006, 2020). "The translational value of IL‐6 as a therapeutic target in cancer treatment also underlines its importance in the inflammation‐associated cancer pathogenesis." (PMID 32638533, 2020). "Many cancer‐associated cytokines such as IL‐1β, IL‐6, and TNF‐α are elevated due to LPS stimulus during oral infection." (PMID 32638533, 2020). "A wealthy body of evidence has shown that the IL-6/JAK/STAT3 signaling pathway is aberrantly activated in many types of cancer and associated with a poor prognosis." (PMID 32127934, 2020). "IL-17 is implicated in early intestinal inflammation and promotes cancer cell survival and proliferation and consequently triggers IL-6 production that activate STAT3 pathway." (PMID 32863742, 2020). "These fibroblasts demonstrated a remarkable similarity to cancer-associated fibroblasts (CAFs), including a high expression of mRNA encoding IL-6." (PMID 33114676, 2020). "Level of IL-6 in Hepatitis B virus-infected patients can be used as a prognostic tool for cancer susceptibility." (PMID 31979357, 2020).